SOX2 (SRY-box transcription factor 2)
Diseases named in the same sentence as SOX2 in open-access papers (continued):
Sharing a sentence is not in itself a finding about the gene and the disease.
Ewing sarcoma (13 papers, 2014 to 2024). A small round cell tumor that lacks morphologic, immunohistochemical, and electron microscopic evidence of neuroectodermal differentiation. "SOX2, a key regulator of pluripotency in ESCs, was initially linked to Ewing’s sarcoma by the observation that MSCs transfected with EWS/FLI1 displayed features of ESFT CSCs." (PMID 26969300, 2016). "Having verified that SOX2 played significant roles in Ewing’s sarcoma cell proliferation and identified some of the underlying regulatory mechanisms in vitro, it was necessary to confirm these findings in vivo." (PMID 26969300, 2016). "The results demonstrate that SOX2 played a central role in promoting Ewing’s sarcoma cell proliferation in vitro and in vivo with the underlying mechanisms expounded." (PMID 26969300, 2016). "Although SOX2 has been strongly implicated with Ewing’s sarcoma cell proliferation and tumorigenesis, the specific regulatory mechanisms remain unclear." (PMID 26969300, 2016). "Therefore, the purpose of this study was to determine the role of SOX2 in the progression of Ewing’s sarcoma and elucidate the underlying mechanisms." (PMID 26969300, 2016). "For example, recent studies showed that targeted silencing of specific GGAA microsatellite genomic loci induced a reduction of SOX2 expression, a key gene in Ewing sarcoma, leading to tumor growth regression in vivo." (PMID 33674598, 2021). "We systematically investigated the role of SOX2 in Ewing’s sarcoma cell lines, human tissue samples and xenograft models." (PMID 26969300, 2016). "In Ewing sarcoma SOX2 enables cell proliferation and survival by regulating p27, p21 and cyclin E to facilitate G1/S phase transition." (PMID 27074562, 2016). "Cancer stem cells in Ewing sarcoma are involved in chemo resistance, with in vitro musculoskeletal sarcoma stem cells expressing SOX2, OCT3/4 and NANOG." (PMID 27074562, 2016). "The results confirmed that SOX2 was highly expressed in Ewing’s sarcoma and was the target of EWS/FLI1." (PMID 26969300, 2016). "Western blotting showed that protein expression of SOX2 was markedly higher in Ewing’s sarcoma samples compared to levels in normal tissues (P < 0.001)." (PMID 26969300, 2016). "In a systematic evaluation of Ewing sarcoma cell lines, human samples and xenograft models siRNA mediated inhibition of SOX2 induces apoptosis and G1/S phase arrest." (PMID 27074562, 2016). "To further demonstrate that SOX2 was implicated in the proliferation and progression of Ewing’s sarcoma, we reactivated the PI3K/Akt pathway after knockdown of SOX2 by overexpressing Akt using plasmids." (PMID 26969300, 2016). "The effect of SOX2 knockdown on cell cycle distribution in Ewing’s sarcoma cells was investigated by flow cytometry in A673 and RD-ES cell lines as an indication of proliferative capacity." (PMID 26969300, 2016). "EWS-FLI-1 represses the miRNA145 promoter and induces expression of SOX2 in Ewing sarcoma to initiate the reprogramming of mesenchymal stem cells towards cancer stem cells." (PMID 27074562, 2016). "Together, these results verified that SOX2 promoted tumor cell proliferation in Ewing’s sarcoma by restraining apoptosis and promoting cell cycle progression via the PI3K/Akt pathway both in vitro and in vivo." (PMID 26969300, 2016). "In conclusion, our in vitro and in vivo data provided comprehensive evidence that SOX2 played a central role in promoting Ewing’s sarcoma cell survival and proliferation." (PMID 26969300, 2016). "Expressions of SOX2 protein in human tissue samples acquired from Ewing’s sarcomas and normal tissues around bones were determined by Western blot and immunohistochemistry (IHC) assays." (PMID 26969300, 2016). "In Ewing sarcoma, SOX2 upregulated by EWS-FLI1 activates PI3K/AKT signaling." (PMID 38331879, 2024). "Intriguingly, accelerated cell apoptosis is ascribed to silencing of SOX2 in Ewing’s sarcoma." (PMID 34521353, 2021).
Ewing sarcoma (continued). "So, further investigation is warranted to determine whether loop regulation of SOX2 and Akt exists in Ewing’s sarcoma." (PMID 26969300, 2016). "SOX2 advanced Ewing’s sarcoma cell survival and proliferation by regulating p21, p27 and cyclin-E to facilitate G1/S phase transition and mediating caspase-3, PARP via both extrinsic (Fas and caspase-8) and intrinsic (caspase-9, Bad, Bcl-2 and XIAP) apoptotic pathways to restrain cell apoptotsis." (PMID 26969300, 2016). "Similarly, the TUNEL assay showed an increase in apoptotic cells, as evidenced by enhanced fluorescence, in both cell lines following knockdown of SOX2, confirming that inhibition of SOX2 induced apoptosis in Ewing’s sarcoma cells." (PMID 26969300, 2016). "Interestingly, EWS-FLI-1 induced the expression of Sox2, Oct-4, and Nanog through miR-145 repression, and they function in a feedback loop with their common target gene, Sox2, which regulates the differentiation and tumorigenicity of Ewing sarcoma cells." (PMID 28115942, 2016). "Our results indicated that SOX2 promoted G1/S transition via regulation of cyclin-E, p21 and p27, supporting previous reports that SOX2 plays a central role in tumor cell proliferation in Ewing’s sarcoma." (PMID 26969300, 2016). "In order to determine whether overexpression of SOX2 advanced the growth capacity of Ewing’s sarcoma cells, two different siRNAs against SOX2 were used to knockdown expression of SOX2 in A673 and RD-ES cell lines." (PMID 26969300, 2016). "The expression of SOX2 was detected in Ewing’s sarcoma samples by WB and IHC." (PMID 26969300, 2016). "By establishing Ewing’s sarcoma xenograft models in mice, we were able to demonstrate that treatment with siRNAs against SOX2 could substantially reduce tumor growth of Ewing’s sarcoma in vivo." (PMID 26969300, 2016). "Cyclin-E binds CDK2 to induce G1/S transition, whereas p21 and p27 repress cyclin-E/CDK2 complex to inhibit the processes; therefore these results indicated that inhibition of SOX2 in Ewing’s sarcoma cells was induced by repression of cyclin-E and activation of p21 and p27." (PMID 26969300, 2016). "Indeed, SOX2 is one of the targets of EWS/FLI, and it has been identified as an oncogenic factor in processes associated with tumor progression, including cell proliferation and tumorigenesis of Ewing Sarcoma family tumors." (PMID 35422060, 2022). "Based on our observation that expression of SOX2 was higher in Ewing’s sarcoma tissues compared to normal tissues around the bones, we hypothesized that downregulation of SOX2 might suppress malignant activity in Ewing’s sarcoma." (PMID 26969300, 2016). "There is an established relationship between EWS-FLI1 and the pluripotency genes SOX2, OCT4, and NANOG in Ewing sarcoma." (PMID 27074562, 2016). "This suggested a functional relationship between SOX2 and the PI3K/Akt signaling pathway in Ewing’s sarcoma cells." (PMID 26969300, 2016). "In order to confirm the relationship between SOX2 and EWS/FLI1 in Ewing’s sarcoma, two small interfering RNAs (siRNAs) were used to knockdown EWS/FLI1 in A673 and RD-ES cells." (PMID 26969300, 2016). "Human Ewing sarcoma cell line also formed spheres at a low frequency rate, which expressed higher levels of Oct3/4, Nanog, STAT3, Sox2, Sox10, and EWS-FLI1, and showed higher drug resistance, similarly to OS cells." (PMID 28115942, 2016). "Moreover, mir145 and SOX2 are regulated by EWS-FLI1, and TARBP2 dependent miRNA maturation appears to be a major regulatory determinant of the cancer stem cells in Ewing sarcoma." (PMID 25243408, 2014). "Moreover, the EWS-FLI1 fusion gene, present in nearly 85 % of Ewing’s sarcomas, induces the expression of Oct4, Nanog, and Sox2 in human pediatric mesenchymal stem cells but not their adult counterparts." (PMID 26412983, 2015).
skin cancer (13 papers, 2013 to 2025). "In fact, it was recently reported that SOX2 and KRAS have interconnections, and that KRAS is mutated in 1.3% of skin cancers." (PMID 36899895, 2023). "SOX2 overexpression has been shown in human tumors, such as breast, ovarian, gastric, pancreatic, colorectal, prostate, and skin cancers, as well as osteosarcomas and glioblastomas." (PMID 34436030, 2021). "A decreased number of SOX2-expressing cells in primary benign and malignant skin tumors has been shown to lead to tumor regression, which is consistent with the vital role of SOX2 in tumor progression." (PMID 34436030, 2021). "A direct role for SOX2 in cell survival is supported by chromatin precipitation studies in skin tumor cells where a number of survival genes were directly regulated by SOX2." (PMID 28623666, 2017). "Another marker expressed in various stem cells, transcription factor Sox2, was also found to be a driver of skin tumors." (PMID 27409834, 2016). "Recently, in a murine skin cancer model SOX2 was shown to be a marker of CSCs in both pre-neoplastic and invasive skin cancer." (PMID 25531390, 2014). "Stem cell markers, CD34 and Sox2, are known to be expressed in chemically induced skin tumors." (PMID 27409834, 2016). "It is interesting to speculate that some of the stem cell survival proteins we have localized in skin cancer stem cells, including Oct4, Sox2, Ezh2 and Bmi-1, may provide such targets." (PMID 24376802, 2013). "Therefore, we examined whether VEGF-C affects cancer stemness in skin cancer cells and found that knockdown of VEGF-C significantly decreased the expression of the CSC markers SOX2, OCT4, KLF4, NANOG, CD133, CD34 and CD44 as well as ALDH activity, which is a hallmark of CSCs." (PMID 27901498, 2017).
thyroid cancer (13 papers, 2014 to 2025). "A log-rank test showed that the SOX2 expression level was associated with PFI for thyroid carcinoma (THCA; p = 0.010), KIRC (p = 0.006), COAD (p = 0.005), LUAD and LUSC (p < 0.001), GBM and MLGG (p < 0.001), and BLCA (p = 0.018)." (PMID 38164286, 2024). "We suppose that SOX2 can be used in diagnostic work as a novel marker for undifferentiated thyroid cancers." (PMID 33489519, 2020). "SOX2 may be a marker of loss of differentiation in thyroid carcinoma." (PMID 33489519, 2020). "To reveal the role of LINC00162 and sorafenib treatment in regulating the stemness of thyroid cancer cells, we evaluated the expression of SOX2, NANOG, CD133, and CD44 in B-CPAP cancer cells." (PMID 40804316, 2025). "Our study grants new insights into the mechanisms of increased BMI1 and SOX2 expression in thyroid cancer and highlights the potential of the Shh pathway inhibitors as anticancer agents for preventing tumor recurrence." (PMID 33499351, 2021). "Clinicopathological analyses of thyroid tumor specimens by immunohistochemical (IHC) staining revealed that BMI1 and SOX2 were highly expressed in thyroid cancer and correlated with Gli1 expression." (PMID 33499351, 2021). "The objective of our current investigation was to determine the role of the Shh pathway in regulating BMI1 and SOX2 expression in thyroid cancer and promoting thyroid tumor growth and development." (PMID 33499351, 2021). "Here we report that BMI1 and SOX2 were highly expressed in thyroid cancer and correlated with Gli1 levels." (PMID 33499351, 2021). "Our study provides evidence that activation of the Shh pathway leads to increased BMI1 and SOX2 expression in thyroid cancer and promotes thyroid CSC-driven tumor initiation." (PMID 33499351, 2021). "In vitro as well as in vivo molecular studies are required to explore the possible role of SOX2 in thyroid carcinoma." (PMID 33489519, 2020). "In the current study, we investigate the pattern of SOX2 immunostaining in a large number of thyroid carcinomas for the first time." (PMID 33489519, 2020). "In the current study, the aim is to investigate the incidence of immunostaining status of SOX2 in thyroid carcinomas and to find the possible relation to clinicopathological features of tumours." (PMID 33489519, 2020). "The current study reported for the first time SOX2 immunostaining on tissue microarrays done from a large number of thyroid carcinomas." (PMID 33489519, 2020). "The study represents for the first time SOX2 immunostaining on a large number of thyroid carcinomas." (PMID 33489519, 2020). "We hereby present for the first time SOX2 immunostaining on the largest cohort of thyroid carcinomas." (PMID 33489519, 2020). "Our ongoing studies suggest that Bmi1, Sox2, and Nanog are highly expressed in thyroid cancer and can be regulated by the Shh pathway." (PMID 29163356, 2017). "Finally, we conducted immunohistochemistry staining to detect the expression of BMI1 and SOX2 in thyroid cancer." (PMID 33499351, 2021). "Our study provides evidence that the Shh pathway regulates BMI1 and SOX2 expression and could be potentially targeted for anti-thyroid cancer therapy." (PMID 33499351, 2021). "In the present study, we demonstrated nuclear SOX2 immunostaining in some thyroid carcinomas." (PMID 33489519, 2020). "In the current study, immunostaining of SRY-box 2 (SOX2) in thyroid carcinoma is investigated." (PMID 33489519, 2020). "SOX2 is a potential marker of these subtypes of thyroid carcinomas and may help in identifying metastatic ATC and PDTC." (PMID 33489519, 2020). "The authors report that the Shh pathway regulates the expression of BMI1 and SOX2, two genes involved in stem cell self-renewal, and that targeting the Shh pathway has little effect on thyroid tumor xenografts but can inhibit the growth of tumor xenografts derived from thyroid cancer stem cells." (PMID 33499351, 2021).
thyroid cancer (continued). "Our present study focused on the expression and regulation of SOX2 and BMI1 by the Shh pathway in thyroid cancer." (PMID 33499351, 2021). "GANT61 also inhibited BMI1 and SOX2 expression in WRO82 cells, a third thyroid cancer cell line with wild-type BRAF gene." (PMID 33499351, 2021). "Nevertheless, our study provides evidence that activation of the Shh pathway plays an important role in regulating SOX2 and BMI1 expression in thyroid cancer." (PMID 33499351, 2021). "Thus, SOX2 expression in thyroid cancer could be regulated by multiple mechanisms." (PMID 33499351, 2021). "It has been reported that both SOX2 and c-MYC have anti-apoptotic effects in gastric, ovarian, head and neck and thyroid cancer cells." (PMID 33089188, 2020). "Third, though it is well established that BMI1 and SOX2 play an important role in regulating stem cell self-renewal in a variety of malignancies, we did not further investigate if this is the case in thyroid cancer." (PMID 33499351, 2021). "SOX2 is highly expressed in 7 ATC specimens and is expressed at higher levels in thyrospheres than in adherent SW1736 cells and in ALDH+ than in ALDH- thyroid cancer cell lines." (PMID 33499351, 2021). "We discovered that SOX2 immunostaining is found in PDTC and ATC while SOX2 immunostaining is lacking in other thyroid cancer." (PMID 33489519, 2020). "Some of these molecules, in particular, Sox2, Nanog, CD133, and ABC G2, are expressed in much higher levels in thyrospheres from fresh thyroid tumors than in monolayers and are expressed at higher levels in ALDH+ than ALDH− thyroid cancer cell lines." (PMID 29163356, 2017). "The rest of the thyroid cancers showed no immunostaining for SOX2." (PMID 33489519, 2020). "Interestingly, SOX2 immunostaining was confined to thyroid carcinomas with lack of differentiation (PDTC and ATC)." (PMID 33489519, 2020). "Whether SOX2 expression is increased in other types of thyroid cancer has not been investigated." (PMID 33499351, 2021).
invasive breast carcinoma (12 papers, 2011 to 2024). A carcinoma that infiltrates the breast parenchyma. "The aims of this study were to determine the frequency of Sox2 positivity in feline invasive mammary carcinomas (FMCs), its relationships with other clinical-pathologic variables, and with patient outcomes." (PMID 33553286, 2020). "Immunohistochemistry for Oct4, Sox2, Nanog, Bmi1, and Klf4 was performed in 319 cases of invasive breast cancer." (PMID 28422735, 2017). "SOX2 expression was detected in 28% of invasive breast carcinoma as well as in 44% of ductal carcinoma in situ (DCIS) lesions." (PMID 21276239, 2011). "Considering cases with any SOX2 expressing cells as positive (score 0 vs. score 1-3) nuclear SOX2 expression was detected in 24 out of 86 analyzed samples of invasive breast carcinoma and 4 out of 9 DCIS." (PMID 21276239, 2011). "Moreover, OSM expression was found to be enriched in Sox2 or Snail-high tumours from an in-house cohort of human invasive breast carcinoma, and positively correlated with the mesenchymal protein S100A7." (PMID 34361105, 2021). "Furthermore, Sox2 expression was detected in 28% of invasive breast carcinoma and 44% in ductal carcinoma." (PMID 29401647, 2018). "Furthermore, a 3q copy number gain (that includes the SOX2 locus) is a stronger predictor of recurrence than grade and other features in invasive breast carcinoma." (PMID 24178749, 2014). "Actually, simultaneous deregulation of miR200cand miR-30c could significantly reduce the survivalrate of breast invasive carcinoma cells via up-regulationof OCT4, SOX2, c-MYC, SNAI1, ZEB1, CDH2 and down-regulation of CDH1 (P=0.02)." (PMID 31376329, 2020). "Actually, deregulation of miR‐204, miR‐200c, miR‐34a, and miR‐10b simultaneously could significantly reduce the survival rate of breast invasive carcinoma via up‐regulation of OCT4, SOX2, KLF4, c‐MYC, NOTCH1, SNAI1, ZEB1, and CDH2 and down‐regulation of CDH1." (PMID 30710426, 2019).
ischemic stroke (12 papers, 2015 to 2025). A stroke disorder caused by obstruction of blood flow to the brain, due to thrombotic (local blood clot formation) or embolic (due to a blood clot or other material traveling from another site) event. "Our results provide evidence that EA treatment induces epigenetic changes to regulate its targets, such as the miR-132/SOX2 axis, which may be a novel mechanism underlying EA treatment for ischemic stroke." (PMID 30618618, 2018). "Although Tbx18-tdT+ cells can generate a small number of Sox2+ i-NSCs following ischemic stroke at both 1 and 3 dpi, they barely produce DCX+ neuroblasts and Olig1+ OL lineage cells." (PMID 39431007, 2024). "It has been reported that EA enhanced neurobehavioral functional recovery against ischemic stroke through targeting of SOX2-mediated axonal regeneration by miR-132." (PMID 33132818, 2020). "In conclusion, EA enhances neurobehavioral functional recovery against ischemic stroke through targeting of SOX2-mediated axonal regeneration by miR-132." (PMID 30618618, 2018). "We assessed the effects of mBMSC and EA on neurogenesis following ischemic stroke using cell proliferation markers (BrdU and Ki67) and differentiation makers (Sox2, Dcx, and PS-NCAM) in the SVZ and surrounding striatum and hippocampus, the main sites associated with general neurogenesis." (PMID 29391466, 2018). "Our results showed that M2-sEV treatment decreased Notch 1 and increased Sox2 expression in activated astrocytes, suggesting that M2-sEVs might potentially be useful for astrocyte reprogramming to neuronal progenitor cells after ischemic stroke." (PMID 33391532, 2021). "There were more BrdU+/SOX2+ cells in the ipsilateral side of the ET-1 group than in the contralateral side, indicating that NSC proliferation was induced in the condition of ischemic stroke (p < 0.01)." (PMID 39697542, 2024). "Furthermore, the immunohistochemistry staining of DCX/BrdU and Sox2/Nestin showed As IV could promote hippocampal neurogenesis and NSC proliferation after ischemic stroke, as well as in vitro." (PMID 32317974, 2020). "In addition, we found that Sox2 expression by OGD treatment was not as remarkable as Klf4 expression, although Sox2 was activated in iSCs following ischemic stroke." (PMID 25945100, 2015).